CD37 (CD37 molecule)
Diseases named in the same sentence as CD37 in open-access papers (continued):
Sharing a sentence is not in itself a finding about the gene and the disease.
tumor (continued). "Targeting CD37 and its downstream effector BCL2 may enhance the anti-tumor efficacy, thereby improving the effectiveness of immunotherapy." (PMID 40250439, 2025). "Moreover, its combination with rituximab demonstrated synergistic tumor suppression in NHL xenograft models, enhancing CD20 expression and potentially improving clinical outcomes with combined CD37- and CD20-targeted therapies." (PMID 40227793, 2025). "In addition, CLDN18 also correlated significantly with markers of activated CD8 + T cells such as MPZL1, CSE1L, CD37, AHSA1, CD3D and IL2RB, after adjusting for tumor purity." (PMID 37438735, 2023). "Ex vivo tumor uptake and tumor-to-blood ratio were higher for [89Zr]Zr-N-sucDf-NNV003 compared to [111In]In-DTPA-IgG (10.9 vs. 3.9%ID/g; P < 0.05 and 2.4 vs. 0.5; P < 0.01), indicating [89Zr]Zr-N-sucDf-NNV003 tumor uptake is CD37-mediated." (PMID 35428777, 2022). "In RAMOS tumor-bearing mice, [89Zr]Zr-N-sucDf-NNV003 tumor uptake was higher than [111In]In-DTPA-IgG at all tested tracer protein doses (10 μg, 25 μg and 100 μg; P < 0.01), further confirming [89Zr]Zr-N-sucDf-NNV003 tumor uptake is CD37-mediated." (PMID 35428777, 2022). "First, we confirmed that DuoHexaBody-CD37 (which lacks cross-reactivity to murine CD37) has a normal clearance rate comparable to WT IgG1-ctrl in tumor-free mice, i.e. in the absence of target binding (data not shown)." (PMID 32341336, 2020). "Intriguingly, immunosuppressive IL-10 secreting B regulatory 1 (BR1) cells are known to support tumor growth have been shown to have downregulated CD37 (2 fold when compared to IL-10 non-secreting cells)." (PMID 33333768, 2020). "The contribution of CD37 to antitumour immunity has been known since the finding that CD37-/- mice have impaired antitumour responses; however, the role of CD37 in the tumour microenvironment is not clear and further investigations are needed." (PMID 31381571, 2019). "Incorporating tumour specific antibodies (anti-CD19, anti-CD20 and anti-CD37) achieved higher delivery and killing efficiency in primary CLL cells ex vivo which may be beneficial for targeting hematologic diseases where FTY720 induces T cell apoptosis." (PMID 27036015, 2016). "The anti-tumor activity of DuoHexaBody-CD37 was also assessed in PDX models, which offer more reliable results for clinical outcomes, because of their more conserved characteristics of the original tumor including heterogeneity, genetic and biological complexity and molecular diversity." (PMID 32341336, 2020). "Similarly, for the treatment of non-Hodgkin lymphoma, the CD37-targeting antibody [212Pb]Pb-NNV003 showed survival benefits in immunocompromised MEC-2 and Daudi tumor models, though biodistribution revealed rapid uptake in some healthy tissues and slow tumor uptake 84​." (PMID 41510167, 2026). "Furthermore, tumor uptake was comparable for 10, 25 and 100 μg [89Zr]Zr-N-sucDf-NNV003, with 10.6 (± 2.7), 12.4 (± 3.4) and 10.1 (± 2.1) %ID/g respectively, indicating CD37 is not saturated in tumor cells by addition of unlabeled antibody at these protein doses." (PMID 35428777, 2022). "In contrast to CD19 CAR, CD37 CAR-T cells were resistant to antigen masking, so tumor cells did not become resistant to it over time." (PMID 33333768, 2020). "While this still supports that 177Lu-lilotomab satetraxetan successfully targets the viable tumor cells in the volume of interest determined from baseline FDG PET, it also indicates that FDG uptake intensity does not necessarily correlates with CD37 expression in tumor." (PMID 35486292, 2022). "Unlike the antigens such as CD20, CD19, or CD37 used to target tumor cells since they are expressed on specific tumor tissues and subpopulations, CD81 is widely expressed in both normal tissues and tumor cells." (PMID 33919192, 2021).
cancer (21 papers, 2012 to 2025). A tumor composed of atypical neoplastic, often pleomorphic cells that invade other tissues. "Expression of CD37, a member of the tetraspanin family, has been involved in metastasis, while nothing is known about the possible role in cancer of CD177, a glycosyl-phosphatidylinositol (GPI)-linked surface protein, normally secreted by neutrophils." (PMID 22253825, 2012). "In terms of cancers, deficiency of CD37 induced the development of B-cell lymphoma." (PMID 32400873, 2020). "Notable downregulated genes included Mki67, Ccn1, Muc1, Atf3, Ntrk2, Arid5b, Igf1r, Igf2bp2, Cd47, and Cd37 (oncogenic function) and integrin-related genes, Itga7, Itga11, Itgam and Notch1 (cancer stem cell markers)." (PMID 39946195, 2025). "Research investigating tetraspanins as therapeutic targets in cancer is already ongoing, exemplified by targeting CD37 in clinical trials for B cell malignancies." (PMID 29896201, 2018). "Tetraspanins play a well-established role in cancer development and progression, and CD37-directed targeted therapies are currently under investigation in clinical trials in patients with B cell malignancies." (PMID 25952155, 2015). "Some of the significant cancer hallmark terms are inflammatory response (CD14, CD69, IL10RA), KRAS signaling up (CD37, IL10RA, GPNMB), IL-6/JAK/STAT3 signaling (CD14, CSF2RB), Interferon Gamma Response (CD69, CSF2RB, IL10RA, VCAM1, SLAMF7), TNF-alpha Signaling via NF-kB (CD69)." (PMID 35486660, 2022). "The mRNA levels of CD37 in different cancers were obtained from GEPIA database." (PMID 32400873, 2020). "Similar with CD3D and CD52, CD79A and CD37 can not only help us monitor specific T–B interactions, which is one of the major parts of the anti-cancer immune response, but can also provide us a new biomarker to evaluate the alteration of cancer microenvironment during tumorigenesis." (PMID 34575089, 2021). "Analysis of cluster-specific genes indicates that these clusters correspond to cancer cells (GFP, Crabp1, Ank), myeloid cells (Aif1, Ctsc, Mpeg1), lymphoid cells (Il2rb, Cd28, Cd3e/g/d, Cd37), and stromal cells (Col1a1/2, Lum, Eln, Dpt), respectively." (PMID 41280683, 2025). "Altogether, TSPAN1, TSPAN15, TSPAN29, and CD151 could support cancer cell growth, while TSPAN31, TSPAN6, CD9, CD37 could inhibit cancer growth." (PMID 36941633, 2023). "Genes related to B and T cell maturation (e.g. CD37, CD79B, JCHAIN, IGLL1, VPREB3, CD52), ribosomal protein genes (RPS-*, RPL-*) and cancer/stress genes (e.g. PRAME, ARHGDIB, FOS, JUN) were within the most significantly deregulated genes between clusters in those samples." (PMID 32415257, 2020).
hematologic malignancies (6 papers, 2016 to 2023). "CD37 was usually expressed in mature B cells, upregulated in other haematologic diseases, and downregulated in IGH::DUX4." (PMID 38115701, 2023). "Recently, a study on CD37 CAR-T cells application in hematologic malignancies has been registered and is currently recruiting patients (NCT04136275)." (PMID 33333768, 2020).
infection (5 papers, 2009 to 2023). The state of being infected such as from the introduction of a foreign agent such as serum, vaccine, antigenic substance or organism. "Tssc6−/− mice also have poor CD8+ responses during infection, which is significantly worse in CD37−/−Tssc6−/− mice." (PMID 25852576, 2015). "We demonstrate that CD37−/− mice are evidently better protected from infection than wild-type mice, which was dependent on C. albicans–specific IgA antibodies." (PMID 19282981, 2009). "Taken together, tetraspanin protein CD37 inhibits IgA responses both in steady state conditions and during infection." (PMID 19282981, 2009). "We report that CD37−/− mice are evidently better protected from infection than wild-type (WT) mice, which was accompanied by increased IL-6 levels and C. albicans–specific IgA antibodies." (PMID 19282981, 2009). "We now report that the B cell–expressed protein CD37 regulates IgA immune responses, both in steady-state conditions and during infection." (PMID 19282981, 2009). "For rDEN2Δ30 infection, higher baseline expression of myeloid nuclear differentiation antigen (MNDA), and cell surface associated cellular processes such as tetraspanin CD37, integral membrane 2B (ITM2B), and genes involved in autophagy (VMP1) was associated with protection from rash." (PMID 34031380, 2021). "CD37 has been reported to inhibit IL-6 signaling upon infection, and during lymphomageneses." (PMID 29896201, 2018). "Moreover, double CD37−/− Tssc6−/− mice displayed an exaggerated hyperproliferative T cell response, and impaired formation of antigen-specific CD8+ T cells after infection." (PMID 29896201, 2018).
hematological cancer (1 paper, 2020). "Although complement-dependent cytotoxicity (CDC) is a powerful Fc-mediated effector function for killing hematological cancer cells, CD37-specific antibodies are generally poor inducers of CDC." (PMID 32341336, 2020).
CD37 also shares sentences with these, for which no sentence is quoted: follicular lymphoma (5 papers); acute lymphoblastic leukemia (3); colon cancer (2); lung carcinoma (2); adrenocortical carcinoma (1); anaplastic large cell lymphoma (1); B-cell prolymphocytic leukemia (1); bladder urothelial carcinoma (1); blood cancers (1); breast carcinoma (1); breast invasive carcinoma (1); cardiovascular diseases (1); cervical squamous cell carcinoma (1); cholangiocarcinoma (1); colon adenocarcinoma (1); endocervical adenocarcinoma (1); ganglioneuroma (1); gastric cancer (1); germ cell cancer (1); hairy cell leukemia (1); hyperglycaemia (1); immune dysfunction (1); Infertility (1); inflammatory bowel disease (1); liver cancer (1); Lymphadenopathy (1); neuroblastoma (1); non-small cell lung carcinoma (1); Obesity (1); osteogenesis imperfecta (1).
A further 7 diseases each share a sentence with CD37 in 1 paper.